DAXX (death domain associated protein)
Diseases named in the same sentence as DAXX in open-access papers (continued):
Sharing a sentence is not in itself a finding about the gene and the disease.
tumor (continued). "For other types of neoplasms, such as those of the hematopoietic system, a limited number of studies support the protumorigenic role of DAXX and HJURP, rendering further investigations necessary to establish their function and possible application in the clinical setting." (PMID 37958340, 2023). "We can therefore conclude that DAXX exerts a possible tumor-promoting role of DAXX in the setting of pediatric AL, specifically ANLL and HR ALL, and could serve as a prognostic marker for relapse in adult AML." (PMID 37958340, 2023). "Numerous prognostic genomic features have been characterized as predictors of survival for pNENs, including mutations in DAXX/ATRX and MEN1, the expression levels of somatostatin receptors 2 and 5, elements of the tumor immune microenvironment, and enzymes involved in hormone metabolism." (PMID 36969744, 2022). "However, in prostate cancer, glioblastoma, and ovarian cancer, DAXX expression is upregulated and promotes tumor progression and chemoresistance." (PMID 36428674, 2022). "We do not yet know the mechanism or significance of these large chromatin domain effects, but suggest they may account for some of the tumor-suppressor functions of DAXX and ATRX." (PMID 36028493, 2022). "Although DAXX and ATRX have both independent and shared functions, the mutually exclusive pattern of mutations in PanNETs strongly implicates their shared function in tumor suppression." (PMID 35976056, 2022). "These cells do not express the death domain-associated protein 6 (DAXX), resulting in the activation of notch signaling and formation of therapy-resistant tumor initiating cells (TICs)." (PMID 35740529, 2022). "In neuroendocrine tumors and breast cancer, DAXX functions as a tumor suppressor." (PMID 36428674, 2022). "Some studies have reported that DAXX/ATRX mutation is correlated with tumor stage and metastasis, and is associated with aggressive clinical behavior, reduced recurrence free survival (RFS) time, and worsening of the tumor-associated survival period." (PMID 36556070, 2022). "Moreover, TGF-β through SMAD, DAXX/HIPK and TAK1/TRAF6 signaling pathways, induced apoptosis and caused cell death, and tumor progression." (PMID 36518397, 2022). "The expression of DAXX is often dysregulated in tumor cells." (PMID 35087762, 2021). "For instance, menin directly interacts with death-domain-associated protein (DAXX), another commonly mutated tumor suppressor gene in pNETs, to repress matrix metalloendopeptidase (MME), a zinc-dependent metalloprotease required for pNET cell proliferation, leading to pNET suppression." (PMID 34680266, 2021). "Most intriguingly, RNA-Seq analysis showed that expressing WT DAXX in G292 also upregulated the pathway related to osteoblast differentiation, suggesting that re-expression of WT ATRX/DAXX in OS cells may stop tumor growth by inducing re-differentiation." (PMID 34069193, 2021). "ATRX/DAXX loss/mutations and ALT positivity are associated with a more aggressive tumour phenotype (larger tumours, grade stage), chromosomal instability, metastatic disease and survival, with the absence of ATRX/DAXX being an independent predictor of survival on multivariable analysis." (PMID 34439335, 2021). "DAXX and ATRX are mutually exclusive inactivating mutations, and no tumor with a mutation in ATRX had a mutation in DAXX." (PMID 34026777, 2021). "Somatic mutations in ATRX, DAXX, or TERT were found in 16% of tumor samples." (PMID 32024817, 2020). "Increasing evidence shows that DAXX functions in tumor progression and its role is multi-faceted." (PMID 31942198, 2020). "DAXX is highly expressed in human organs, particularly various tumor tissues." (PMID 32641734, 2020). "Our results demonstrated that DAXX is negatively correlated with tumor metastasis and that DAXX is down-regulated at the metastatic site compared to the primary lesion, implying that DAXX may act as a metastasis suppressor in CRC." (PMID 31942198, 2020).
tumor (continued). "Consistent with the analysis in our tumor samples, SLX4IP deficiencies in our cell lines are mutually exclusive with ATRX, DAXX, SMARCAL1, and H3.3, raising the possibility that SLX4IP may represent another gene deficiency associated with ALT activity." (PMID 31447390, 2019). "Therefore, effective treatments should not only target TA in cancer cells but should also be aimed atmodulatingthe proper function of the ATRX/DAXX/H3.3 complex to destroy tumor cells." (PMID 30625996, 2019). "A critical finding was that DAXX is a tumor suppressor that may regulate the biological mechanism through the CD24 or β-catenin pathway in patients with CRC." (PMID 31614769, 2019). "DAXX can promote malignant phenotypes in vitro and tumor growth and progression in vivo." (PMID 31350900, 2019). "While these studies conclude that DAXX activity may serve a cancer-protective function, recent work has shown, conversely, that the presence of DAXX in some cases mayenhance tumor growth as well as generate resistance to treatment." (PMID 29479426, 2018). "DAXX has also been found to promote tumor growth in a mouse xenograft model of prostate cancer." (PMID 29479426, 2018). "It is noted that some well-established associations like mutations in ATRX and DAXX (death-domain associated protein) for ALT as well as TERT promoter mutations for telomerase-positive cells are absent in many tumor samples." (PMID 29776332, 2018). "However, while IT and MLP tumours from human and mouse clustered together, MEN1-like tumours formed a compact subgroup that clustered far from the mouse model and were enriched in mutations of chromatin remodeling genes (MEN1, DAXX, ATRX)." (PMID 29321190, 2018). "Because DAXX promotes SREBP-mediated gene expression and de novo lipogenesis, and the maintenance of lipid production by SREBPs is critical for cell proliferation and tumor growth, we hypothesized that DAXX expression levels impact cell proliferation in vitro and tumor growth in vivo." (PMID 37045819, 2023). "Mutations of menin and DAXX/ATRX have not been shown to be mutually exclusive in the same tumour." (PMID 34439335, 2021). "Tumor-associated missense mutations in the substrate recognition domain of SPOP disrupt substrate binding and ubiquitination, leading to the accumulation of oncogenic substrates, such as steroid receptor coactivator (SRC3), c-MYC and death-domain-associated protein (DAXX)." (PMID 33138914, 2020). "Furthermore, mutations in TSC1, TSC2, JAK1, and DAXX appeared at the level of ATC, making it likely that some of these genetic events influenced the development of this undifferentiated tumor type - although only the TSC1 and DAXX mutations were carried along to the metastatic ATC component." (PMID 35582231, 2020). "The identification of mutations in ATRX/DAXX genes in sporadic NENs, as well as the high burden of mutations scattered throughout the multiple endocrine neoplasia type 1 (MEN-1) gene in both sporadic and inherited syndromes, provided new insights into the molecular biology of tumour development." (PMID 31443481, 2019). "Hence, to achieve effective tumor cell senescence and apoptosis by blocking telomere lengthening, not only should the telomerase-associated pathway be targeted, but the proper functioning of the ATRX/DAXX/H3.3 complex should be retained." (PMID 30625996, 2019). "Conversely, genes linked to DNA-damage responses and apoptotic pathways (H2AX, DAXX, ANXA1) demonstrated relatively higher expression in prehabilitation-treated tumor regions." (PMID 41596590, 2026).
tumor (continued). "Certain mutations were more frequently observed in MGMT IHC negative tumors, particularly those involving genes that regulate the cell cycle, such as DAXX and CDKN2A, which were altered in only primary tumor specimens." (PMID 39825572, 2025). "In contrast, in the bladder, expression of DAXX and ATRX declined with increasing tumour grade (p < 0.05)." (PMID 41472189, 2025). "A central mechanistic link between ALT and tumor biology lies in ATRX and DAXX, chromatin remodelers critical for the deposition of histone variant H3.3 at telomeric and pericentromeric regions." (PMID 41148828, 2025). "Although expression levels did not distinguish between non-malignant and malignant bladder tissues, UC showed a reduction in DAXX and ATRX expression with increasing tumour grade." (PMID 41472189, 2025). "In contrast, in the urinary bladder, DAXX and ATRX expression declined with increasing tumour grade (between grades 2 and 3)." (PMID 41472189, 2025). "All neoplasms were investigated with immunohistochemistry for neuroendocrine markers (Synaptophysin, Chromogranin-A), ATRX, DAXX, ARX, and PDX1 transcription factors." (PMID 39331358, 2024). "Our data presented above demonstrated that the DAXX–SREBP interactions are critical for lipogenic gene expression, lipid synthesis and tumor growth." (PMID 37045819, 2023). "MME was also found to be required for proliferation of the neuroendocrine cells that were co-repressed by MENIN and DAXX, and in vivo experiments proved that knockdown of MME suppressing the tumor growth." (PMID 35360859, 2022). "In G2, CD56, CgA, NSE, vimentin and Ki-67 were higher in tumour tissue compared to those in non-tumour, and levels of CD44, CD45, CK7, DAXX, synaptophysin and PDX1 were lower in tumour tissue relative to those in non-tumour tissue." (PMID 36362433, 2022). "Other markers including Ki67, PCNA, DAXX, CD24, CD44, CD31, MENA, Laminin, ECAD, PCAD and CDX2 and CK14 showed different trends in expression between tumour and non-tumour with qRT-PCR compared to IHC." (PMID 33906633, 2021). "The markers synaptophysin, PCNA, DAXX, laminin and CD14 had similar expression levels in tumour and non-tumour tissue." (PMID 33906633, 2021). "To assess the role of DAXX in tumour development in vivo, we injected MKN45 cells transfected with a lentivirus that overexpresses DAXX, or lentivirus that carries vector alone in nude mice." (PMID 32203224, 2020). "DAXX inhibition in PTEN-depleted populations decreases oncogene expression and promotes the expression of tumor suppressors, inhibiting tumor growth in vivo and improving animal survival." (PMID 31752169, 2019). "Moreover, because the crosstalk in signaling networks of these targets may affect the efficacy of the novel agents, effective treatments should not only target TA in cancer cells but should also be aimed at modulating the proper function of the ATRX/DAXX/H3.3 complex to destroy tumor cells." (PMID 30625996, 2019). "This approach would inactivate the DAXX pathway for tumor promotion, and consequently restore the activity of the DAPK1 and DAPK3 tumor suppressors." (PMID 26097870, 2015). "The expression of ALCAM, CN130, DAXX, GAL1, PHF6 and XPA were significantly correlated with tumor grade and stage." (PMID 23819605, 2013). "ATRX/DAXX mutations and associated alternative lengthening of telomeres (ALT) are common in non-functioning PanNETs and associated with aggressive tumor behavior." (PMID 39954168, 2025). "Alterations in the expression of DAXX and/or ATRX can influence tumour biology." (PMID 41472189, 2025). "Thus, the role of DAXX and ATRX in tumour biology must always be interpreted within the specific tumour type, both in human and veterinary oncology." (PMID 41472189, 2025).
tumor (continued). "The chaperone-independent activity of DAXX exerts oncogenic effects, as opposed to the tumor-suppressive effects of its chaperone activity." (PMID 38297159, 2024). "DAXX’s SUMO-binding property is critical to the DAXX-SREBP2 interaction, de novo lipogenesis, DAXX’s recruitment to lipogenic genes, and in vivo tumor growth." (PMID 37045819, 2023). "In this work, DAXX is identified as a regulator of oncogenic lipogenesis through its interaction with SREBP1/2, leading to activating lipogenic gene expression programs and the promotion of cancer cell proliferation in vitro and tumor growth in vivo." (PMID 37045819, 2023). "DAXX/ATRX immunohistochemistry staining in tumor cells is used as a tissue-based biomarker in non-metastasized settings, especially G2 tumors with potential progressive behavior." (PMID 35326628, 2022). "We discovered in this study that a phytoestrogen, either naringenin or resveratrol, potently inhibits breast TICs in vitro and in vivo without stimulating proliferation of tumor cells specifically by increasing the DAXX protein." (PMID 32864429, 2020). "We confirmed the presence of two driver genes, MEN1 and DAXX, mutations in which were found in one-fifth of PNET samples but not in other tumor types." (PMID 32586046, 2020). "Wild-type AGS cells were not able to form tumours in nude mice, but in contrast, formed visible tumours when DAXX was silenced in the cells." (PMID 32203224, 2020). "In both works, tumor subgroups and mutations in MEN1, DAXX/ATRX, or the mTOR pathway genes did not associate." (PMID 30657883, 2019). "Further study is needed to resolve this controversy regarding the prognostic value of chromatin remodeling alterations including MEN1, DAXX, and ATRX, which may be tumor stage and grade-specific." (PMID 31692857, 2019). "In this type of tumours, a consistent correlation between ALT phenotype and inactivation of either ATRX or DAXX has been reported; however, ALT-positive cases that preserve expression of ATRX and DAXX indicates the presence of other activators." (PMID 29751586, 2018). "For example, in GBM cells lacking the tumor suppressor PTEN, there is a DAXX-dependent increase in the expression of oncogenes, and inhibition of DAXX in this context can suppress tumor growth." (PMID 29479426, 2018). "In addition to DAXX, immunohistochemistry studies will include DAPK1 and DAPK3 so as to establish a relationship between DAXX and the DAPK1/3 tumor suppressors." (PMID 26097870, 2015). "While reduced expression or inactivation of other tumour suppressor genes, including PTEN, NF1, ATRX and DAXX, has been associated with specific GBM subtypes, we are not aware of any other wild type gene that behaves as a tumour suppressor in some GBM subtypes and as an oncogene in others." (PMID 27083054, 2016). "An inverse correlation has been found between DAXX and DAPK1/3 mRNA expression in a diverse collection of human tumor cell lines and tumor specimens [Submitted], suggesting that DAXX's role as a transcriptional repressor of DAPK1/3 is broadly relevant to tumor biology and is not restricted to PCa." (PMID 26097870, 2015). "Lastly, given the fact that DAXX/ATRX loss is not observed in NET from other origin, except a small fraction of lung NET, it may be a useful biomarker for the identification of primary tumours in the setting of metastasis of unknown origin." (PMID 33975869, 2022). "However, partial ER agonists could be beneficial if one is identified that does not stimulate tumor growth, but yet increases DAXX protein expression and potently inhibit TICs, thus potentially preventing tumor relapse." (PMID 32864429, 2020). "In summary, the patterns of DAXX and ATRX expression varied between non-malignant samples and tumour tissues in the prostate." (PMID 41472189, 2025).
tumor (continued). "Markers CD24, CD44, PDX1, synaptophysin, CD49, CDX2, CD45, DAXX, PCAD and CK7 had lower expression in the tumour relative to that in the non-tumour with the exception of one patient." (PMID 36362433, 2022). "mRNA levels of PCNA, DAXX, laminin and CD14 in tumour tissue were equal to the levels seen in the non-tumour tissue whereas protein expression was increased for PCNA and decreased for laminin and CD14 in the tumour tissue relative to the non-tumour tissue." (PMID 33906633, 2021). "Upregulation of the anti-apoptotic genes BCL2L2, BAG3, and downregulation of pro-apoptotic genes DAXX, FAF1, PAK1, DFFA, ENDOG was found in reprogrammed tumours pointing to a cell cycle arrest without engagement of the apoptotic pathway." (PMID 29662623, 2018).